MARCKSL1 (MARCKS like 1)
Description:
Controls cell movement by regulating actin cytoskeleton homeostasis and filopodium and lamellipodium formation. When unphosphorylated, induces cell migration (By similarity). When phosphorylated by MAPK8, induces actin bundles formation and stabilization, thereby reducing actin plasticity, hence restricting cell movement, including neuronal migration (By similarity). May be involved in coupling the protein kinase C and calmodulin signal transduction systems (By similarity).
Synonyms: MacMARCKS; MLP; MRP; F52; MLP1
Tractability: Antibody: UniProt places it where antibodies can reach, with high confidence; its Gene Ontology location is reachable by antibodies, with high confidence. PROTAC: ubiquitination databases record sites on it; its protein half-life has been measured.
Gene: Protein-coding gene on chromosome 1 (32,333,827 to 32,336,233, reverse strand). Ensembl gene ENSG00000175130.
Subcellular location: Cytoplasm, cytoskeleton; Cell membrane
Subcellular location (Human Protein Atlas): Plasma membrane; Cytokinetic bridge; Endoplasmic reticulum; Mitotic spindle; Primary cilium
Gene Ontology:
Molecular function: protein binding; actin filament binding; calmodulin binding
Biological process: actin filament organization; central nervous system development
Cellular component: extracellular exosome; plasma membrane; cytoplasm; cytoskeleton
Genetic constraint (gnomAD): Loss-of-function variants: 5 observed, 11.62 expected, observed/expected ratio (o/e) 0.43, 90% interval 0.22 to 0.9. The synonymous counts are far from expectation, so gnomAD's model fits this gene poorly and the ratio says little. Missense variants: 274 observed, 228.81 expected, observed/expected ratio (o/e) 1.2, 90% interval 1.08 to 1.32. Synonymous variants: 126 observed, 97.09 expected, observed/expected ratio (o/e) 1.3, 90% interval 1.12 to 1.5.
Homologues: Orthologues: chimpanzee MARCKSL1 (100% identical), macaque MARCKSL1 (100% identical), mouse Marcksl1 (96% identical), dog MARCKSL1 (95% identical), pig MARCKSL1 (94% identical), guinea pig MARCKSL1 (84% identical), rat Marcksl1 (83% identical), rat LOC103689966 (82% identical), rabbit MARCKSL1 (81% identical). Paralogues in human: MARCKS (44% identical).
Diseases named in the same sentence as MARCKSL1 in open-access papers:
MARCKSL1 is named in the same sentence as 41 diseases in open-access papers, as found by Europe PMC text mining. Sharing a sentence is not in itself a finding about the gene and the disease. The quoted sentences say what the papers report.
lung adenocarcinoma (6 papers, 2022 to 2024). A carcinoma that arises from the lung and is characterized by the presence of malignant glandular epithelial cells. "MARCKSL1 is known to promote the progression of lung adenocarcinoma by regulating epithelial-to-mesenchymal transition (EMT)." (PMID 37775701, 2023). "Liang found that MARCKSL1 promotes the progression of lung adenocarcinoma by regulating epithelial-mesenchymal transition." (PMID 35126478, 2022). "MARCKSL1 promoted the progression of lung adenocarcinoma by regulating epithelial–mesenchymal transition (EMT)." (PMID 36300089, 2022). "In addition, the function of MARCKSL1-2 in docetaxel resistance of lung adenocarcinoma cells was investigated." (PMID 38473229, 2024). "In lung adenocarcinoma cells, MARCKSL1 promotes proliferation, migration, and invasion." (PMID 38478326, 2024). "This hypothesis was further validated by in vivo experiments using a mouse xenograft tumor model that supported MARCKSL1-2 overexpression leading to attenuated docetaxel resistance in lung adenocarcinoma tumors." (PMID 38473229, 2024).
breast carcinoma (4 papers, 2016 to 2025). "This study was performed as an independent validation of the prognostic value of MARCKSL1 protein expression in LN- breast cancer patients under 71 years of age." (PMID 30856208, 2019). "MARCKSL1 expression was evaluated in 151 operable T1,2N0M0 LN- breast cancer patients by immunohistochemistry." (PMID 30856208, 2019). "We aim to validate MARCKSL1 protein expression as a prognostic marker for distant metastasis-free survival (DMFS) in a new cohort of LN- breast cancer patients." (PMID 30856208, 2019). "In addition, in another breast cancer cell line experiment, MARCKSL1 was shown to suppresses LOXL2 induced oncogenesis and stimulating apoptosis, thereby acting as a tumor suppressor." (PMID 30856208, 2019). "In breast cancer cell lines, MARCKSL1 knockdown results in decreased migration." (PMID 30856208, 2019). "Therefore, in the current study we aim to validate the prognostic value of MARCKSL1 protein expression in a new cohort of LN- breast cancer patients." (PMID 30856208, 2019). "Additionally, in a separate study that involved breast cancer metastasis to the bone, MARCKSL1 was reported to be upregulated." (PMID 27502506, 2016). "In addition to breast cancer, there was significant upregulation of MARCKSL1 in lung cancer, rhabdomyosarcoma, leiomyosarcoma, prostate cancer and uterine cancer." (PMID 27502506, 2016). "In addition, the prognostic value of MARCKSL1 in breast cancer has been gradually investigated." (PMID 37470685, 2023). "We speculate that while MARCKSL1 was prognostic in an earlier population, changes in chemotherapy guidelines have altered the overall survival and the specific need for prognostic factors in Norwegian breast cancer patients." (PMID 30856208, 2019). "Protein expression of Myristoylated alanine-rich C kinase substrate like-1 (MARCKSL1) has been identified as a prognostic factor in lymph-node negative (LN-) breast cancer patients." (PMID 30856208, 2019). "These included genes such as SCUBE3, MARCKSL1 and PGK1 in lung cancer, SOX4 and GNAS in breast cancer and hepatocellular carcinoma, HEG1 in hepatocellular carcinoma, PLS3 in pancreatic adenocarcinoma, FBN1 and SPARC in gastric cancer and CST1 in gastric cancer and breast cancer." (PMID 40430098, 2025).
hepatocellular carcinoma (3 papers, 2023 to 2025). A malignant tumor that arises from hepatocytes. "The present findings suggested that MARCKSL1, a potential therapeutic target for hepatocellular carcinoma and MVI progression, may be crucial for improving therapeutic strategies and clinical outcomes, particularly for patients with MVI." (PMID 39944086, 2025). "Based on our preliminary findings, we hypothesized that MARCKSL1 plays a significant role in MVI and tumour progression in hepatocellular carcinoma." (PMID 39944086, 2025). "The role of MARCKSL1 has not been extensively demonstrated in hepatocellular carcinoma." (PMID 39944086, 2025).
prostate carcinoma (3 papers, 2010 to 2016). A carcinoma that arises from epithelial cells of the prostate gland. "Counter-intuitively, knockdown of MARCKSL1 in different tissue contexts, specifically the neural tissue, and prostate cancer cell line (PC-3) resulted in an abrupt increase in migration." (PMID 27502506, 2016).
Anxiety (2 papers, 2022 to 2024). Intense feelings of nervousness, tension, or panic often arise in response to interpersonal stresses. "Overexpressed Marcksl1 induces anxiety-like behaviors in Marcksl1 Tg C57BL/6N mice, however, decreased Marcksl1 ameliorates anxiety-like behaviors in mice." (PMID 36672612, 2022).
epilepsy (2 papers, 2024 to 2025). A brain disorder characterized by episodes of abnormally increased neuronal discharge resulting in transient episodes of sensory or motor neurological dysfunction, or psychic dysfunction. "Interestingly, several of the most highly connected mRNAs have been associated with epilepsy and other neurodegenerative disorders [e.g., Rere, Marcksl1, Ttr65–67 and Discussion], supporting the biological relevance of our approach." (PMID 38961125, 2024). "According to the ROC curves, the expression level of key genes including CTSD, CREG1, PECAM1, ZNF101, RRM2B, MARCKSL1, and MAP2K4 demonstrated a certain accuracy in classifying epilepsy and control groups (0.7 < AUC < 0.9)." (PMID 40520613, 2025).
esophageal squamous cell carcinoma (2 papers, 2023 to 2025). Esophageal squamous cell carcinoma (ESCC) is a type of esophageal carcinoma (EC) that can affect any part of the esophagus, but is usually located in the upper or middle third. "In addition, MARCKSL1 has been implicated in the progression of various malignancies, including breast, lung, and esophageal squamous cell carcinoma." (PMID 40221783, 2025). "High MARCKSL1 expression is positively correlated with poor prognosis in esophageal squamous cell carcinoma (ESCC) patients with lymph node metastasis." (PMID 35894387, 2023). "Emerging evidence indicates that myristoylated alanine‐rich C kinase substrate like 1 (MARCKSL1) is involved in the progression of esophageal squamous cell carcinoma (ESCC)." (PMID 35894387, 2023).
lymph node metastasis (2 papers, 2023). "High expression of MARCKSL1 was positively correlated with lymph node metastasis and associated with worse patient survival rates in ESCC." (PMID 35894387, 2023). "Higher expression of MARCKSL1 was positively correlated with lymph node metastasis and associated with worse survival rates of patients with ESCC." (PMID 35894387, 2023). "High MARCKSL1 expression is positively correlated with poor prognosis in ESCC patients with lymph node metastasis." (PMID 35894387, 2023). "Moreover, our study found that EV-derived MARCKSL1 had the ability to discriminate metastatic sites (liver), and our study covered the validation and analysis of TNM stage, lymph node metastasis status and metastatic sites." (PMID 37340044, 2023).
Sepsis (2 papers, 2012 to 2022). Sepsis is defined as life-threatening organ dysfunction caused by a dysregulated host response to infection. "Observed disparities in expression of the DEG, e.g., high average disparity in murine and pediatric sepsis samples for the CCL4 and MARCKSL1 genes, may reflect a bias within the mapping or the underlying genomic features." (PMID 23024636, 2012).
asthma (1 paper, 2018). "Therefore, further research is required to assess the precise mechanisms by which MARCKS and MARCKSL1 contribute to development and regeneration, providing professionals with the molecular tools that will help them design new therapies for illnesses such as asthma, cancer, and spinal cord injury." (PMID 29788979, 2018).
colorectal cancer (1 paper, 2023). A primary or metastatic malignant neoplasm that affects the colon or rectum. "The mechanism of MARCKSL1 in colorectal cancer metastasis should be further studied to guide clinical treatment." (PMID 37340044, 2023). "As a protein associated with the occurrence and development of various tumors, MARCKSL1 has been mainly verified as a potential tumor marker or a new therapeutic target in lung cancer, liver cancer, colorectal cancer and other tumors." (PMID 37340044, 2023). "MARCKSL1 has been proposed to be a potential differentiator between metastatic and nonmetastatic colorectal cancer by proteomics analysis in relevant clinical studies." (PMID 37340044, 2023). "The present study demonstrated that the level of circulating EV-derived MARCKSL1 in patients with metastatic colorectal cancer was significantly higher than that in patients with nonmetastatic colorectal cancer and healthy people." (PMID 37340044, 2023). "In our previous study, we found that MARCKSL1 was significantly highly expressed in plasma EVs of patients with metastatic colorectal cancer by analyzing the proteomic data of plasma EVs in small samples of healthy people and patients with metastatic and nonmetastatic colorectal cancer." (PMID 37340044, 2023). "In this study, MARCKSL1 was initially defined as a specific marker for distinguishing metastatic and nonmetastatic colorectal cancer, but it was not sensitive in distinguishing healthy and newly diagnosed nonmetastatic colorectal cancer, which was analogous to the results of previous studies." (PMID 37340044, 2023). "Therefore, we studied the relationship between the plasma EV-derived MARCKSL1 level and the tumor stage and clinicopathological markers of CRC in healthy people, patients with nonmetastatic CRC and colorectal cancer to assess its value in the early diagnosis of CRC progression." (PMID 37340044, 2023).
dementia (1 paper, 2022). Loss of intellectual abilities interfering with an individual's social and occupational functions. "The increased dementia risk in individuals with high levels of plasma SVEP1, HE4, CDCP1, SIGLEC‐7, MARCKSL1, CRDL1, or RNAS6 is a novel finding." (PMID 34338426, 2022).
esophageal cancer (1 paper, 2023). A primary or metastatic malignant neoplasm involving the esophagus. "Taken together, these results support that MARCKSL1 mediates the mobility and migration of esophageal cancer cells." (PMID 35894387, 2023). "MARCKSL1 may be a new biomarker and therapeutic target for esophageal cancer." (PMID 35894387, 2023). "To explore whether MARCKSL1 modulates tumor progression in patients with esophageal cancer, we analyzed gene expression from The Cancer Genome Atlas (TCGA) database and obtained RNA‐seq fragments per kilobase million (FPKM) values from the TCGA Genomic Data Commons (GDC) portal." (PMID 35894387, 2023). "The mRNA level of MARCKSL1 in esophageal carcinomas (n = 182) was notably higher than that in adjacent noncancerous tissues (n = 286)." (PMID 35894387, 2023).
melanoma (1 paper, 2021). A malignant, usually aggressive tumor composed of atypical, neoplastic melanocytes. "The expression levels of LTBP4 and CDHR1 in melanoma tissues were notably lower than those in the control group, while MARCKSL1 expression in melanoma tissues was notably higher than that in the control group." (PMID 35252214, 2021). "Next, the diagnostic ability of these three biomarkers in discriminating melanoma from the control samples demonstrated favorable diagnostic value, with the AUC values of 0.985 (95% CI 0.951–1.000) in LTB4, 0.949 (95% CI 0.839–1.000) in CDHR1, and 0.911 (95% CI 0.720–1.000) in MARCKSL1." (PMID 35252214, 2021).
metastatic colorectal cancer (1 paper, 2023). "Circulating EV-derived MARCKSL1 is significantly elevated in the plasma of patients with metastatic colorectal cancer and can be used as a potential diagnostic marker for the early diagnosis of mCRC." (PMID 37340044, 2023). "Based on this, the purpose of this study was to determine whether EV-derived MARCKSL1 can distinguish metastatic colorectal and nonmetastatic colorectal cancer and whether it can be used as an early diagnostic biomarker of metastatic colorectal cancer." (PMID 37340044, 2023).
Stroke (1 paper, 2025). Sudden impairment of blood flow to a part of the brain due to occlusion or rupture of an artery to the brain. "Specifically, PPARα KO led to increased expression levels of Gadd45b, Nppa, Hdc, Lcn2, Il6, Sox4, Marcksl1, Saa3, Ucn2, Met, Dusp10, Elovl7, Ngf, C3, Il11, Hmox1, Alox5, Tnfsf9, Angptl4, Plin2, H19, Csf2rb, Atf3, and Col7a1 following stroke." (PMID 40362325, 2025).
systemic lupus erythematosus (1 paper, 2020). An autoimmune multi-organ disease typically associated with vasculopathy and autoantibody production. "In the third trimester, systemic lupus erythematosus and proteasome were enriched in the acute disease while Fc gamma R-mediated phagocytosis (VAV1, MARCKSL1, WASF2, DNM2, HCK, MAP2K1 genes) and adherens junction (ACTG1, WASF2, SMAD4, CSNK2B, EP300 genes) represented the subclinical category." (PMID 32012176, 2020).
cancer (19 papers, 2012 to 2025). A tumor composed of atypical neoplastic, often pleomorphic cells that invade other tissues. "MARCKSL1, the most up-regulated protein, is associated with increased migratory potential in cancer cells." (PMID 34857819, 2021). "Dysregulation of MARCKS or MARCKSL1 has also been implicated in many different cancers, where they affect tumorigenesis, metastasis and angiogenesis." (PMID 29788979, 2018). "MARCKS-related protein (MARCKSL1) is a widespread, highly conserved membrane-associated protein whose hyperexpression promotes cell proliferation via the ErbB2-mediated signalling pathway and facilitates angiogenesis and growth in carcinoma cells in vivo." (PMID 35719407, 2022). "The combinations of these markers (MARCKSL1 + SLC9A3R1 + RHOD) when used together (ScreenCell cocktail) led to the staining of 100% of the cancer cells with the uppermost intensity." (PMID 40429857, 2025). "MARCKSL1 was primarily expressed in the MCs_2, MCs_4, and MCs_5 subtypes, indicating the potential association with MVI and cancer malignancy." (PMID 39944086, 2025). "In turn, the interaction of LOXL2 with myristoylated alanine-rich C kinase substrate-like 1 (MARCKSL1) improves the survival of cancer cells by inhibiting the MARCKSL1-induced apoptosis." (PMID 39329988, 2024). "In PCa, MARCKSL1 is strongly induced and up-regulated, and the knockdown of MARCKSL1 affects actin stability and migration in cancer cells." (PMID 38829766, 2024). "A growing body of evidence implicates the myristoylated alanine-rich C-kinase substrate (MARCKS), and the highly homologous MARCKS-like protein 1 (MARCKSL1) in cancer migration and metastasis." (PMID 36230850, 2022). "DNA methylation of cg17086398 in SERINC2 was inversely associated with myristoylated alanine-rich C-kinase substrate like 1 (MARCKSL1) expression, which is involved in migration of cancer cells." (PMID 32697766, 2020). "Among them, the MARCKSL1 is related to the occurrence and development of many types of cancers." (PMID 36644230, 2023). "Each gene in the risk evaluator, PLXNA1, MARCKSL1, IQGAP3, PFN2, PON1, and TAK, has been reported to be associated with the prognosis or progression of cancer." (PMID 37954858, 2023). "Moreover, the oncogenes c-Myc and MARCKSL1 participate in the development and progression of cancers." (PMID 36494341, 2022). "Using ScreenCell technology to isolate cancer cells spiked into normal blood, we tested the protein expression of all corresponding genes in vitro using the double immunocytochemistry method and validated MARCKSL1, SLC9A3R1, and RHOD as the most expressed markers." (PMID 40429857, 2025). "Similarly, unphosphorylated, membrane bound MARCKS or MARCKSL1 have been shown to promote lamellipodium formation, axon outgrowth and cell motility in neurons and cancer cells in some studies, whereas phosphorylated, cytosolic MARCKS has been shown to promote cell motility in other studies." (PMID 29788979, 2018). "Both MARCKS and MARCKSL1 are activated by phosphorylation, suggesting that MARCKS-targeted therapies could be used to treat cancer metastasis." (PMID 36230850, 2022). "Notably, previous studies revealed that IGF2BP1, acted as a m6A reader, played an oncogenic role in cancer cells, through stabilizing methylated mRNAs of oncogenic proteins, including FSCN1, TK1, MARCKSL1, and MYC." (PMID 33853613, 2021). "In a prospective clinical study including 305 cancer patients, MARCKSL1 has a strong prognostic value in lymph node-negative cancer patients, especially in those with high proliferation." (PMID 31215439, 2019). "TTC3 and MARCKSL1 show no cancer gene linking, of which MARCKSL1 are increasedly expressed in some vincristine-resistant cell lines." (PMID 22830977, 2012).